INS (insulin)
Diseases named in the same sentence as INS in open-access papers (continued):
Sharing a sentence is not in itself a finding about the gene and the disease.
diabetes (continued). "Kim and Kim 45 developed a glucose-responsive protein delivery system model enabling glucose-responsive protein release in vitro, offering potential for closed-loop insulin delivery in diabetes management." (PMID 41346708, 2026). "Subsequent relapse of diabetes and restart of insulin treatment was reported in 2 of the patients at the ages of 5 and 6.5 years." (PMID 41500078, 2026). "Automated insulin delivery (AID) systems have significantly advanced diabetes management, progressively reducing user interactions required for optimal glucose management." (PMID 41555051, 2026). "All forms of pancreatogenic (type 3c) diabetes are characterised by impaired insulin secretion but maintenance of significant islet beta cell mass, even in the presence of virtually complete destruction of the exocrine component of the gland." (PMID 41665665, 2026). "Diabetes Mellitus is a chronic metabolic disorder characterized by elevated blood glucose due to defects in insulin secretion or action, or both, leading to serious short- and long-term complications if not effectively managed." (PMID 42196776, 2026). "People with diabetes rely on exogenous insulin to reduce blood glucose levels, compensating for insulin resistance or impaired pancreatic β-cell function." (PMID 41726984, 2026). "LRRC8A abnormality is involved in various aspects of diabetes, including insulin resistance and impaired insulin secretion by pancreatic β-cells." (PMID 41439137, 2026). "Both insulin and sulphonylurea derivatives are diabetes drugs used primarily to lower serum glucose concentrations." (PMID 41486865, 2026). "We report a 41‐year‐old female with Type 1 Diabetes Mellitus (T1DM) who developed severe euDKA after initiating tirzepatide for weight loss while on empagliflozin and basal–bolus insulin therapy." (PMID 41584389, 2026). "This co-design study identified priorities of older adults with diabetes and healthcare professionals to be addressed in system-wide insulin safety interventions for surgical admissions." (PMID 41782301, 2026). "Diabetes mellitus is a chronic metabolic disorder characterized by impaired carbohydrate, lipid, and protein metabolism resulting from defects in insulin secretion, insulin action, or both." (PMID 41503501, 2026). "In this randomized trial, insulin sensitizers or sitagliptin facilitated SIIT implementation by reducing insulin requirements and accelerating near‐normoglycemia achievement in adults with newly diagnosed type 2 diabetes mellitus and marked hyperglycemia." (PMID 41521023, 2026). "Nevertheless, the pleiotropic effect of diabetes medications or insulin therapy on the Lp(a)-redox relationship in patients with diabetes cannot be excluded." (PMID 41164877, 2026). "Since her blood glucose levels rose with the initiation of hydrocortisone, on HD + 17 we switched the patient’s diabetes treatment from IDeg/Asp to a combination of basal insulin degludec and regular insulin to allow for more precise dosage adjustment." (PMID 41536580, 2026). "Policy-makers must also ensure access to insulin and related treatments necessary for the effective management of people with diabetes." (PMID 41409098, 2026). "Together, these resultsindicate that the developed casNP/insulin/C10 holds promisein rendering an effective and drinkable oral insulin formulation formanaging diabetes." (PMID 41442621, 2026). "Various laboratory examinations, including tests for HbA1c, C-peptide, glucose, insulin, acetone, and blood gases, are necessary for diabetes detection." (PMID 41540069, 2026). "Our multivariate analysis revealed strong associative factors for developing PDR in this population, including duration of diabetes, Hispanic race, microalbuminuria and macroalbuminuria, and use of insulin and beta blockers." (PMID 41509989, 2026). "Diabetes mellitus (diabetes) is a metabolic disorder that is characterized by hyperglycemia, which develops as a result of defective insulin secretion, insulin action, or both." (PMID 41494166, 2026).
diabetes (continued). "Despite initially requiring insulin, her diabetes resolved entirely following glucocorticoid withdrawal." (PMID 41503046, 2026). "Type 1 diabetes mellitus (T1DM) is an autoimmune disease that damages insulin‐producing pancreatic cells, often appearing in childhood." (PMID 41573056, 2026). "Not only does exercise improve glycaemic control, it also induces improvements in insulin sensitivity, blood lipid profile and inflammation in individuals with T2DM." (PMID 40551391, 2026). "In 2022, the mother passed away peacefully at the age of 88, her diabetes controlled with insulin injections for decades." (PMID 41490382, 2026). "Similar to this previous report, the possibility is suggested that decreased insulin secretion in DK/DKA with type 1 diabetes mellitus and possible α cell insulin resistance in HHS with type 2 diabetes mellitus are causes of hyperglucagonemia." (PMID 41292690, 2026). "The blue cluster captures experimental studies conducted in animal models and includes terms such as “rat”, “mouse”, “experimental diabetes mellitus”, “glucose blood level”, “insulin”, “liver”, and “gene expression”." (PMID 41599361, 2026). "The development of frailty changes the metabolic profile of older people, and their insulin resistance and diabetes trajectory, which will have an impact on the choice of glucose-lowering agents and the goals of therapy." (PMID 42042580, 2026). "Diabetes mellitus (DM) is a multifactorial group of metabolic disorders characterized by chronic hyperglycemia resulting from impaired insulin secretion, insulin resistance, or both." (PMID 41599361, 2026). "This retrospective observational study investigated the association between sleep disorders and alterations in glucose metabolism, insulin secretion, and glucagon regulation in patients with type 2 diabetes mellitus (T2DM)." (PMID 41686553, 2026). "Implantable insulin replacement therapy in the dams effectively reversed the detrimental effects of maternal diabetes on hippocampal excitability, prepulse inhibition, and object-place memory, but not anxiety-like behavior or set-shifting." (PMID 41590515, 2026). "Diabetes is one of the most prevalent chronic diseases globally, primarily characterized by hyperglycemia, impaired insulin secretion, and chronic inflammation." (PMID 41509193, 2026). "Diabetes mellitus is a metabolic disorder characterized by chronic hyperglycemia, primarily resulting from insufficient insulin secretion and insulin resistance [...]." (PMID 42187772, 2026). "The encapsulated pancreatic islet cells can continuously secrete insulin, providing a viable treatment for diabetes, while encapsulated hepatocytes support liver regeneration." (PMID 41216376, 2026). "After adjusting for HbA1c, BMI, and diabetes duration, patients on insulin therapy showed significantly higher NOX2 levels compared to those on oral agents alone." (PMID 41607455, 2026). "The disease manifests mainly as type 1 diabetes mellitus (T1DM), a condition requiring insulin due to inadequate hormone production, and type 2 diabetes mellitus (T2DM), which emerges predominantly from reduced insulin effectiveness in peripheral body tissues." (PMID 41517209, 2026). "The obesity-metabolic syndrome-diabetes continuum is driven by interconnected mechanisms including insulin resistance, dysfunctional adiposity, chronic inflammation and progressive cardio-renal-metabolic injury." (PMID 42198407, 2026). "Diabetes mellitus is a chronic and increasingly prevalent metabolic disorder characterized by persistent hyperglycemia, resulting from defects in insulin secretion, insulin action, or both." (PMID 42195389, 2026). "Type 2 diabetes mellitus (T2DM) is a chronic metabolic disorder characterized by insufficient insulin production or ineffective insulin utilization, leading to impaired glucose uptake and persistent hyperglycemia." (PMID 41599356, 2026).
diabetes (continued). "Diabetes mellitus is a chronic metabolic disorder characterized by impaired insulin signaling and glucose homeostasis." (PMID 42294182, 2026). "There is some evidence in the literature that it promotes glucose uptake and improves insulin sensitivity and thus helps to control diabetes and prevent its complications in the initial stages." (PMID 42211608, 2026). "For patients with PDR, we identified significant independent associations with microalbuminuria and macroalbuminuria, Hispanic ethnicity, duration of diabetes, and the use of insulin and beta‐blocker medications." (PMID 41509989, 2026). "The COVID-19 pandemic, caused by SARS-CoV-2, has resulted in a significant increase in insulin resistance and new-onset diabetes among recovered individuals." (PMID 41890193, 2026). "Conventional management of diabetes via injection or external insulin pumps suffers from inconvenience and inability to accurately maintain blood glucose levels." (PMID 41849446, 2026). "We also showed that expression levels of MafA and PDX-1 in pancreatic β-cells were recovered by insulin therapy especially at an early stage of diabetes, which ameliorated β-cell function." (PMID 41585322, 2026). "Diabetes mellitus (DM) is a complex metabolic disease characterized by a persistent chronic hyperglycemic state attributable to defective insulin secretion and impaired glucose utilization." (PMID 41601904, 2026). "Type 2 diabetes mellitus (T2DM) is characterized by reduced insulin sensitivity and chronic systemic inflammation in metabolic tissues, including adipose tissue, skeletal muscle, and the liver." (PMID 41509193, 2026). "C-peptide measurement is of use clinically as a marker of β cell function, estimates of which are diagnostically and prognostically important in diabetes, and can also be used to calculate insulin secretion rates." (PMID 41355468, 2026). "The global surge in diabetes prevalence, coupled with the limitations of insulin therapy and pancreatic/islet transplantation, has propelled cell therapy to the forefront as a promising strategy for potentially curing the disease." (PMID 41597265, 2026). "Magnesium is a crucial component for insulin production and glucose metabolism, and diminished serum magnesium levels are commonly noted in type 2 diabetes mellitus (T2DM)." (PMID 42220770, 2026). "Insulin use was strongly associated with SMBG (A0R=7.02, 95% CI=2.44-20.19, P<0.001), whereas the presence of diabetes complications was negatively associated with SMBG (A0R=0.57, 95% CI=0.33-0.98, P=0.043)." (PMID 42261361, 2026). "The results indicate that individuals who have insulin as part of their regimens have lower diabetes knowledge scores compared to those using OHA only (β = − 0.35660, 95%CI [− 0.622, − 0.0909], p = 0.009)." (PMID 41311517, 2026). "Collectively, these findings highlight a complex and bidirectional relationship between 5-HT and insulin in the regulation of glycemic levels and the pathophysiology of diabetes." (PMID 41424854, 2026). "This likely reflects several factors: more advanced and severe diabetes requiring therapeutic intensification, prolonged exposure to chronic hyperglycemia before insulin initiation, and potentially more marked treatment resistance." (PMID 41607455, 2026). "Although insulin and metformin formulations have long constituted the foundation of diabetes care, a paradigm shift in T2D management has been observed with the advent of novel pharmacotherapies." (PMID 42307179, 2026). "Using a rodent model of insulin-requiring diabetes, we evaluated the effects of daily SSTR2a administration with insulin dosing (study A: 8 days) and repeated exposures to hypoglycemia (study B: 4× over 11 days) on glucagon and glycemia." (PMID 41502124, 2026). "This is partially due to the behavioral changes required for diabetes self-management (e.g. adjusting insulin doses with food intake and exercise)." (PMID 41484931, 2026).
diabetes (continued). "Diabetes, characterized by insufficient insulin, is a complex condition affecting various organs such as the liver, muscles, and adipose tissue, as insulin regulates glucose production." (PMID 41540069, 2026). "Results were consistent after adjustment for donor insulin dependence as a proxy for severity and recipient factors including diabetes status." (PMID 41767737, 2026). "Diabetes mellitus (DM) represents a complex metabolic disorder characterized by chronic hyperglycemia due to impaired insulin secretion or action." (PMID 41595319, 2026). "For older adults with long-term insulin-treated diabetes, managing frailty, preserving body mass index (BMI) and muscle strength and mitigating hypoglycaemia risk are key challenges." (PMID 42141826, 2026). "Digital health technology (DHT), which includes continuous glucose monitoring, insulin delivery devices, and related mobile health apps, can support diabetes self-care and thereby improve diabetes outcomes." (PMID 41886736, 2026). "Diabetes mellitus is a metabolic condition characterized by elevated blood glucose levels stemming from impaired insulin production or functionality." (PMID 41517209, 2026). "Glucose-responsive smart insulin delivery systems that mimic the pancreatic insulin release system can improve the health and quality of life of patients with diabetes." (PMID 42198149, 2026). "When it comes to patients with diabetes treated with insulin pumps, few studies have explored telemedicine’s efficacy." (PMID 41198916, 2026). "The patient was managed symptomatically with insulin therapy for diabetes, prednisolone for autoimmune hepatitis, and hormone replacement for hypopituitarism." (PMID 41531690, 2026). "The combination of negative diabetes autoantibodies, preserved C-peptide (2.1 ng/mL), and subsequent insulin independence was most consistent with an A-β+ ketosis-prone diabetes phenotype unmasked by acute stress." (PMID 41836962, 2026). "While aspartame's low-calorie structure provides an advantage for metabolic diseases such as obesity and diabetes, its potential effects on insulin sensitivity and gut microbiota have led to different conclusions." (PMID 42022336, 2026). "At the systemic level, adipocyte browning enhances energy expenditure, improves insulin sensitivity, and mitigates lipid accumulation, making it a promising target for the treatment of obesity, type 2 diabetes mellitus, and other metabolic syndromes." (PMID 41683747, 2026). "The guidelines summarize the diagnostics of type 1 diabetes mellitus, including accompanying autoimmune diseases, insulin therapy regimens and glycemic target values." (PMID 42162462, 2026). "The intervention promoted high insulin prescription accuracy (99%) and diabetes supply provision (88%)." (PMID 41551323, 2026). "One such application is the modeling of glucose-insulin regulation, which plays a critical role in understanding diabetes dynamics." (PMID 41551260, 2026). "Despite being essential for diabetes management, insulin formulations exhibit inconsistent performance due to their relatively fragile stability." (PMID 41726984, 2026). "ADA recommends CGM in all patients with diabetes using intensive insulin regimens of multiple daily injections (MDIs) or continuous subcutaneous insulin infusion as well as patients using basal insulin." (PMID 41601933, 2026). "Concurrently, insulin therapy was initiated, and the patient received diabetes education for the management of newly diagnosed diabetes." (PMID 42312067, 2026). "Mainly used in patients on insulin to assess endogenous insulin secretion.Urine C-peptide has been utilised in decision models for identifying monogenic diabetes in adult and paediatric populations." (PMID 41355468, 2026). "Cohort comorbidities included smoking (18%) and diabetes (8.9%; 5.3% non-insulin dependent; 3.6% insulin-dependent)." (PMID 41732429, 2026).
diabetes (continued). "Due to insufficient insulin secretion, patients with type 1 diabetes mellitus (T1DM) are prone to blood glucose fluctuations ranging from hypoglycemia to hyperglycemia." (PMID 41766716, 2026). "Cissus verticillata (plant-insulin) is used in the Brazilian popular medicine to treat symptoms of diabetes." (PMID 41752474, 2026). "The patient is a 19-year-old male with normal growth and development, presenting with a 9-year history of diabetes that remains poorly controlled despite intensive subcutaneous insulin therapy." (PMID 42039128, 2026). "Screening was considered beneficial by 91% of primary HCPs and by all diabetes centres, emphasising reduced efforts for insulin initiation and long-term care." (PMID 42017309, 2026). "Insulin (5 U/day), melatonin (10 mg/kg), and quercetin (40 mg/kg) were administered for 30 days after confirmation of diabetes." (PMID 42021540, 2026). "Type 1 diabetes mellitus (T1DM) patients require lifelong insulin therapy; however, iatrogenic hypoglycemia remains a major clinical challenge, with high incidence in adults." (PMID 42117040, 2026). "We report a 69-year-old woman with a background of insulin-treated diabetes mellitus, hypertension, hypercholesterolemia, and prior hyperthyroidism, who presented with acute altered consciousness and cognitive dysfunction." (PMID 41994747, 2026). "The liver plays a pivotal role in glucose metabolism and insulin signaling, and its dysfunction exacerbates diabetes-related complications." (PMID 41549124, 2026). "Previous work under hyperketogenic diets demonstrated that ketosis elevates Cer in muscle, and to a lesser extent in plasma, driving insulin resistance via mechanisms similar to diabetes." (PMID 41527118, 2026). "We report the case of a 68-year-old man with type 2 diabetes mellitus treated with basal-bolus insulin, metformin, and linagliptin who presented with vomiting, confusion, fatigue, hypotension, and reduced level of consciousness." (PMID 42137698, 2026). "Students faced difficulties managing diabetes with school or college schedules, particularly morning classes, due to insulin and meal timing." (PMID 41529039, 2026). "This instability carries significant cost implications: Some individuals spend over $1000 per month on insulin, and these high prices influence one in six Americans with diabetes to ration their insulin supplies." (PMID 42057375, 2026). "Hypertension, diabetes mellitus, dyslipidemia, prior stent implantation, established coronary artery disease, male sex, and use of β-blockers and oral antidiabetic/insulin therapy were more prevalent in the LVSD (+) group." (PMID 41594214, 2026). "Participants reported gradual self-learning in diabetes management, including dietary regulation, portion control, insulin administration, and glycemic control." (PMID 41529039, 2026). "Insulin edema is an uncommon complication that typically arises soon after initiating insulin therapy, most often in individuals with newly diagnosed diabetes or poorly controlled hyperglycemia." (PMID 41476905, 2026). "Protein ingestion plays a key role in the secretion of both insulin and glucagon, making it a key regulator of blood glucose levels in health and diabetes." (PMID 41602572, 2026). "Chronic cardiovascular and pulmonary disease, severe chronic kidney disease, moderate to severe liver disease, dementia, insulin-requiring type II diabetes mellitus or diabetes treated with oral antidiabetic drugs, tumors, HIV, and obesity were included." (PMID 41562685, 2026). "In patients with type 1 diabetes mellitus in the DK/DKA group, shorter duration of hyperglycemic symptoms was associated with hyperglucagonemia and also with lower endogenous insulin secretion." (PMID 41292690, 2026). "Diabetes mellitus with resistance to insulin administered SC or IM (DRIASM), an alternative terminology for this condition, has been postulated to be due to tissue insulin degradation or absorption abnormalities." (PMID 41472947, 2026).